HSD17B11 (hydroxysteroid 17-beta dehydrogenase 11)
Description:
Can convert androstan-3-alpha,17-beta-diol (3-alpha-diol) to androsterone in vitro, suggesting that it may participate in androgen metabolism during steroidogenesis. May act by metabolizing compounds that stimulate steroid synthesis and/or by generating metabolites that inhibit it. Has no activity toward DHEA (dehydroepiandrosterone), or A-dione (4-androste-3,17-dione), and only a slight activity toward testosterone to A-dione. Tumor-associated antigen in cutaneous T-cell lymphoma.
Synonyms: 17bHSD11; retSDR2; DHRS8; PAN1B; SDR16C2; 17-BETA-HSD11; 17-BETA-HSDXI
Tractability: Small molecule: a structure with a bound ligand is known; it has a binding pocket of medium quality. Antibody: UniProt predicts a signal peptide or a membrane-spanning region. PROTAC: ubiquitination databases record sites on it; its protein half-life has been measured.
Target class: Enzyme; Oxidoreductase
Gene: Protein-coding gene on chromosome 4 (87,336,515 to 87,391,219, reverse strand). Ensembl gene ENSG00000198189.
Subcellular location: Endoplasmic reticulum; Lipid droplet
Subcellular location (Human Protein Atlas): Lipid droplets
Pathways (Reactome):
Metabolism: Estrogen biosynthesis
Gene Ontology:
Molecular function: estradiol 17-beta-dehydrogenase [NAD(P)+] activity; protein binding; steroid dehydrogenase activity; oxidoreductase activity, acting on the CH-OH group of donors, NAD or NADP as acceptor
Biological process: androgen catabolic process; estrogen biosynthetic process
Cellular component: cytoplasm; lipid droplet; cytosol; endoplasmic reticulum
Genetic constraint (gnomAD): Loss-of-function variants: 9 observed, 14 expected, observed/expected ratio (o/e) 0.64, 90% interval 0.39 to 1.12. The upper end of that interval is the gene's LOEUF score, 1.12, which puts it in group 4 of 6, group 1 being the genes least tolerant of losing a copy. Missense variants: 195 observed, 218.61 expected, observed/expected ratio (o/e) 0.89, 90% interval 0.79 to 1. Synonymous variants: 71 observed, 87.44 expected, observed/expected ratio (o/e) 0.81, 90% interval 0.67 to 0.99.
Homologues: Orthologues: macaque HSD17B11 (95% identical), rabbit HSD17B11 (88% identical), pig HSD17B11 (86% identical), mouse Hsd17b11 (83% identical), guinea pig HSD17B11 (82% identical), rat Hsd17b11 (81% identical), chimpanzee HSD17B11 (79% identical), dog HSD17B11 (78% identical), tropical clawed frog hsd17b11 (60% identical). Paralogues in human: HSD17B13 (63% identical), SDR16C5 (42% identical), RDH10 (41% identical), DHRS3 (34% identical), RDH12 (25% identical), RDH11 (25% identical), HSD17B6 (23% identical), RDH16 (23% identical), SDR9C7 (22% identical), HSD11B2 (21% identical), HSD17B12 (21% identical), DHRS9 (21% identical), and 13 more.
Diseases named in the same sentence as HSD17B11 in open-access papers:
HSD17B11 is named in the same sentence as 23 diseases in open-access papers, as found by Europe PMC text mining. Sharing a sentence is not in itself a finding about the gene and the disease. The quoted sentences say what the papers report.
prostate carcinoma (3 papers, 2010 to 2022). A carcinoma that arises from epithelial cells of the prostate gland. "The androgen-metabolizing enzyme HSD17B11 has been implicated in advanced prostate carcinoma." (PMID 35704598, 2022). "HSD17B11 is nearly ubiquitously expressed, but is also overexpressed in some human malignancies, including advanced prostate cancer and non-small cell lung cancer cell lines, as compared to normal tissues or cell lines." (PMID 35535493, 2022). "Searching for evidence in PubMed for association between HSD17B11 and melanoma brings up no hits but is associated with seminal vesicle invasion in prostate cancer." (PMID 20642836, 2010).
colorectal cancer (2 papers, 2020 to 2021). A primary or metastatic malignant neoplasm that affects the colon or rectum. "The lnc-HSD17B11-1:1 was found to promote colorectal cancer progression through the lnc-HSD17B11-1:1/miR-338-3p/MACC1 axis." (PMID 34101736, 2021).
hepatic diseases (2 papers, 2021 to 2024). "The results shed new light on the role of MST3, STK25, and MST4, as well as their interactions with PDCD10, MAP4K4, and HSD17B11, in the control of liver lipid homeostasis and metabolic dysfunction–associated steatotic liver disease susceptibility." (PMID 39395791, 2024). "On the other hand, the loss of function of HSD17B13 caused by genetic variations has positive effects in hepatic diseases, and HSD17B11 could be a target for the treatment of pancreatic diseases." (PMID 34503201, 2021).
pancreatic cancer (2 papers, 2021). "Interestingly, elevated expression of HSD17B11 is associated with shorter overall survival of pancreatic cancer patients." (PMID 34503201, 2021). "Among 39 differentially expressed factors, seven up-regulated genes (CAV2, CIDEC, HILPDA, HSD17B11, NCEH1, RAB5A, and SQLE) and two down-regulation genes (BSCL2 and FITM1) were significantly associated with overall survival of pancreatic cancer patients." (PMID 34078402, 2021). "The precise role of HSD17B11 in pancreatic cancer still needs to be elucidated." (PMID 34503201, 2021). "We further identified that enhanced expression of 7 genes namely CAV2, CIDEC, HILPDA, HSD17B11, NCEH1, RAB5A, and SQLE are associated with significantly shorter overall survival whereas elevated expression of BSCL2 and FITM1 correlates with longer overall survival of pancreatic cancer patients." (PMID 34078402, 2021). "The role of HSD17B11 in pancreatic cancer has not been elucidated." (PMID 34078402, 2021).
breast carcinoma (1 paper, 2019). "The low expression of HSD17B11 and ITGA2 and the high expression of VIM and ABHD17C have all been validated by recent sequencing studies on breast cancer, reflecting the accuracy of these two rules." (PMID 31456818, 2019).
coronary artery disease (1 paper, 2021). "In a integrated microarray analysis, HSD17B11 was one of the up regulated genes in coronary artery disease, and pathway enrichment analysis revealed that differentially expressed genes in coronary artery disease were mostly enriched in the superpathway of steroid hormone biosynthesis, and so on." (PMID 33980183, 2021).
esophageal cancer (1 paper, 2023). A primary or metastatic malignant neoplasm involving the esophagus. "The overexpression of the HSD17B11 protein promotes lipid droplet formation in esophageal cancer, thereby facilitating the development of esophageal cancer." (PMID 38202722, 2023).
non-small cell lung carcinoma (1 paper, 2022). A group of at least three distinct histological types of lung cancer, including non-small cell squamous cell carcinoma, adenocarcinoma, and large cell carcinoma. "The role of HSD17B11 in (S)–3 cytotoxic activity was further confirmed using two different small-interfering RNAs (siRNA) to down-regulate HSD17B11 in U2OS and in the non-small cell lung carcinoma cell line A549, in which CRISPR/Cas9-mediated HSD17B11 inactivation also conferred (S)–3 resistance." (PMID 35535493, 2022).
thyroid cancer (1 paper, 2025). "We used LASSO Cox regression to construct a model for the evaluation of thyroid cancer prognosis, and a risk model consisting of six genes (ACSL5, HSD17B11, CCL5, NCF2, PSME1, and ACTB) was subsequently developed." (PMID 40299520, 2025). "Further validation using qRT–PCR in 100 paired thyroid cancer and adjacent normal tissues revealed consistent upregulation of ACSL5 and NCF2 in tumour tissues and downregulation of HSD17B11, CCL5, and ACTB." (PMID 40299520, 2025).
tumor (5 papers, 2017 to 2025). "Survival analysis of these genes in tumour samples identified seven genes that were associated with prognosis, including ACSL5, HSD17B11, CCL5, NCF2, PSME1, ACTB, and CYBB." (PMID 40299520, 2025). "Collectively, all these data together indicated that lnc-HSD17B11-1:1 facilitates proliferation and tumor growth of CRC cells." (PMID 32595704, 2020). "Then bioinformatics analyses and Base Scope assay both revealed that lnc-HSD17B11-1:1 was located in cytoplasm of CRC tumor tissues." (PMID 32595704, 2020). "This study shows that the reader protein YTHDF1 may regulate tumor lipid metabolism by reducing the translation efficiency of the target gene HSD17B11." (PMID 35568876, 2022). "Further research showed that FTO promoted the occurrence and development of EC by mediating lipid metabolism, and HSD17B11 could be a key component in mediating FTO-dependent tumor stemness." (PMID 35568876, 2022). "We found lnc-HSD17B11-1:1 and MACC1 are co-overexpressed in CRC tumor tissues." (PMID 32595704, 2020).
cancer (2 papers, 2020 to 2022). A tumor composed of atypical neoplastic, often pleomorphic cells that invade other tissues. "However, the potential role for HSD17B11 in cancer progression remains to be established." (PMID 35535493, 2022). "To investigate the biological function of lnc-HSD17B11-1:1 in CRC cells, we first detected lnc-HSD17B11-1:1 expression levels in CRC cell lines and found high expression in cancer cell lines in comparison with colorectal normal one NCM460, especially in HCT116 and SW480." (PMID 32595704, 2020).
HSD17B11 also shares sentences with these, for which no sentence is quoted: cervical squamous cell carcinoma (1 paper); diabetes (1); Hepatic fibrosis (1); hepatoma (1); liver steatosis (1); lung carcinoma (1); melanoma (1); metabolic disease (1); Obesity (1); osteosarcoma (1); pancreatic diseases (1); sarcopenia (1).